SLC7A11 (solute carrier family 7 member 11)
Diseases named in the same sentence as SLC7A11 in open-access papers (continued):
Sharing a sentence is not in itself a finding about the gene and the disease.
tumor (continued). "In conclusion, our investigation demonstrated for the first time that TRIM7, as a tumor suppressor, induced ferroptosis via targeting SLC7A11 in GC, which provided a new strategy for the molecular therapy of GC by upregulating TRIM7." (PMID 38509147, 2024). "Tumor cells overexpress SLC7A11, promoting the export of glutamate from the tumor, leading to glutamate accumulation in the tumor microenvironment." (PMID 39769177, 2024). "SLC7A11 inhibition resulted in selective killing of cancer cells in vitro and tumor growth inhibition in vivo." (PMID 39061826, 2024). "Nevertheless, Slc7a11-KD in tumor cells had little impact on CD8+ T cells in draining lymph nodes (DLN) and spleens." (PMID 38360744, 2024). "To further investigate the occurrence of ferroptosis, we conducted immunohistochemical staining for GPX4 and SLC7A11 in the subcutaneous tumor tissues of the nude mice." (PMID 39771583, 2024). "Firstly, we compared the capability of cystine uptake between T cells and tumor cells, confirming that SLC7A11, the functional subunit of system Xc-, was upregulated in various human tumors." (PMID 38360744, 2024). "Through the promotion of GSH synthesis, SLC7A11 aids tumor cells in resisting oxidative stress and cytotoxicity induced by chemotherapeutic drugs, thereby facilitating tumor cell proliferation and survival." (PMID 39600313, 2024). "Aberrant DNA methylation of the disulfidptosis genes was also investigated in cancers, such as hypermethylation of GYS1 in CHOL, and hypomethylation of SLC7A11 in most tumor types." (PMID 39605832, 2024). "Several studies have reported that T cells overexpressing either Slc7a11 or cystathionine-gamma-lyase, the key enzyme converting methionine to cysteine, exhibit enhanced tumor suppression." (PMID 38360744, 2024). "It has been commonly accepted that SLC7A11 plays an important role to promote tumor cell proliferation by inhibiting ROS accumulation in multiple types of cancer cells." (PMID 38862581, 2024). "Within the tumor microenvironment, interactions involving SLC7A11 between immune cells and tumor cells play a significant role in influencing tumor survival and proliferation." (PMID 39040097, 2024). "In this work, we found the relationship of the MMR genes and the expression of NCKAP1 and SLC7A11, which was essential to anti-tumor immunity." (PMID 38230212, 2024). "A HepG2 cell–transplanted tumor model was established in nude mice, and CK inhibited the growth of transplanted tumors in nude mice, p-FOXO1 was decreased in tumor tissues, and SLC7A11 and GPX4 expressions were also down-regulated after CK treatment." (PMID 38664638, 2024). "Solute carrier family 7 member 11 (SLC7A11) exerts a tumor-promoting effect via inhibition of ferroptosis." (PMID 38545555, 2024). "This process can either relieve BACH1’s downregulation of SLC7A11, inhibit ferroptosis, promote tumor growth, or upregulate the expression of pro-migration targets and accelerate tumor metastasis." (PMID 39664391, 2024). "There was good concordance between SLC7A11 (which encodes xCT), NQO1, GCLC and GCLM median expression levels across tumours, providing an ‘antioxidant signature’ associated with the NRF2 transcriptional programme." (PMID 39690148, 2024). "In various tumor cells, studies have shown that SLC7A11 inhibits ferroptosis, a form of cell death, by mediating cystine uptake and maintaining glutathione synthesis." (PMID 39125853, 2024).
tumor (continued). "The Spearman correlation analysis confirmed a positive correlation between circUPF2 and SLC7A11 mRNA expression in HCC tumor tissues (P < 0.001, R2 = 0.69)." (PMID 38811968, 2024). "In vivo data further demonstrated that high SLC7A11 promoted primary tumor growth but repressed tumor metastasis." (PMID 38539832, 2024). "They discovered that CD8+ T cells can release IFN-γ to downregulate SLC3A2 and SLC7A11, components of System XC-, inhibiting cystine uptake by tumor cells." (PMID 39061859, 2024). "In this paper, we summarize the structure and biological functions of SLC7A11, and discuss its potential role in tumor therapy, which provides a new direction for precision and personalized treatment of tumors." (PMID 39040097, 2024). "IHC demonstrated that Ki-67 and SLC7A11 expression in tumor tissues were decreased in response to erastin treatment, but SOCS2 expression was elevated." (PMID 38267746, 2024). "Prior investigations have concentrated on the role of ferroptosis in tumor cells, highlighting how SLC7A11-mediated ferroptosis and phenotypic alterations in TAMs profoundly modify the HCC tumor microenvironment and promote tumor proliferation." (PMID 38397869, 2024). "For instance, many tumor cells are more sensitive to ferroptosis when SLC7A11 or antioxidant transcription factor Nrf2 levels are elevated." (PMID 38469234, 2024). "For example, solasonine treatment disrupted glutathione metabolism and induced SLC7A11‐mediated ferroptosis to block tumour formation and metastasis in mouse xenograft models." (PMID 38682349, 2024). "And we performed histopathology analysis to further detect the expression level of SLC7A11 in mouse tumor sections of each group." (PMID 39420439, 2024). "We posit that the ERO1α/IL-6/STAT3/SLC7A11 pathway is critical for mTORC1-mediated ferroptosis resistance and tumor growth and that it can be targeted for the treatment of cancers associated with dysregulated mTORC1 signaling." (PMID 38610018, 2024). "Subsequently, we categorized the 37 LUAD patients into high and low SLC7A11 expression groups based on SCL7A11 expression in tumor tissue and plotted Kaplan–Meier curves." (PMID 38655266, 2024). "Overall, the mTORC1/ERO1α/IL-6/STAT3/SLC7A11 signaling cascade, which is also present in human cancer cells, plays a critical role in ferroptosis resistance and tumor progression." (PMID 38610018, 2024). "Our results indicate that ERO1α promotes tumor progression and ferroptosis resistance, at least partially, by upregulating SLC7A11." (PMID 38610018, 2024). "Previous studies have documented the overexpression of SLC7A11 in various cancer types, with a demonstrated role in tumor promotion." (PMID 38317842, 2024). "Emerging data suggest that elevated SLC7A11 expression in precancerous lesions and tumor tissues correlates with adverse outcomes and therapy resistance." (PMID 39420439, 2024). "Differential expression analysis conducted on the TCGA-KIRC dataset revealed that SLC7A11 was significantly upregulated in tumor tissues compared to that in normal tissues." (PMID 38862242, 2024). "CD8+ T cells facilitate tumor cell ferroptosis by releasing IFNγ and inhibiting the expression of SLC7A11." (PMID 38267442, 2024). "Meanwhile, IHC verified the differential expression of SLC7A11 in PCa tissues and adjacent normal tissues, which indicated the potential of inhibitting tumor growth by triggering disulfidptosis." (PMID 38191330, 2024). "Tumor cells have the ability to increase the expression of SLC7A11 and GPX4, which helps protect them from ferroptosis induced by radiotherapy." (PMID 38816377, 2024). "Among tumor types, UCEC was found to present the most widespread somatic mutations of the disulfidptosis genes, such as SLC7A11 (92 %), NCKAP1 (85 %), LRPPRC (75 %), and OXSM (75 %)." (PMID 39605832, 2024).
tumor (continued). "Recent studies have found that overexpression of SLC7A11 promotes tumor growth, in part because it inhibits iron apoptosis, a regulated form of cell death induced by excessive lipid peroxidation." (PMID 38334964, 2024). "High expression of SLC7A11 significantly accelerates disulfidptosis in tumour cells under glucose starvation." (PMID 39590840, 2024). "SLC7A11, a functional subunit of system Xc−, is upregulated in tumors and aids tumor cells to outcompete CD8+ T cells for cystine uptake, ultimately inducing CD8+ T-cell exhaustion and ferroptosis." (PMID 39614322, 2024). "Upon the failure of immunotherapy, the ANO1 gene is upregulated, activating the PI3K-Akt pathway, resulting in the expression of NRF2/SLC7A11 proteins and inhibiting oxidative stress in tumor cells." (PMID 38853203, 2024). "Similar with the data from subcutaneous tumor model, IHC and western blotting analyses revealed significantly lower expression levels of Ki67, SLC7A11, and GPX4 in the SFN treatment group." (PMID 39657365, 2024). "This is consistent with the absence of proliferation defects upon KD of the major amino acid transporters (SLC1A5, SLC7A1, SLC7A5 and SLC7A11) in K562 tumours." (PMID 38605144, 2024). "Despite CD8+ T cells up-regulating Slc7a11 expression under cystine starvation, it is worth noting that Slc7a11 expression in tumor-infiltrated CD8+ T cells was significantly lower than that in tumor cells." (PMID 38360744, 2024). "More importantly, immunofluorescence assays illustrated higher SLC7A11 expression was relevant to higher STIM1 expression compared with tumor tissues from HCC patients with low STIM1 expression." (PMID 39281833, 2024). "We provided several lines of evidence demonstrating that HMGA1 plays a critical role in maintaining intracellular redox balance and promoting tumor proliferation by cooperating with ATF4 to activate the transcription of SLC7A11." (PMID 38383528, 2024). "The tumour suppressor BAP1 enhances ferroptosis by regulating the expression of cystine transporter SLC7A11, thus improving the control of tumour growth." (PMID 36600313, 2023). "Radiotherapy is reported to suppress the expression of SLC7A11, which enhances tumor lipid oxidation and sensitizes tumor cells to ferroptosis agonists in vitro and in vivo." (PMID 38124786, 2023). "It has been demonstrated that in most tumors, the SLC7A11 coding code protein, through its specific biological properties, alters the microenvironment of tumor growth and thus promote tumor growth." (PMID 37399661, 2023). "The SLC7A11-GSH-GPX4 system plays a crucial role as the main defense against ferroptosis in tumours." (PMID 38273826, 2023). "The potential mechanism of SLC7A11 in tumor development and progression include resistance to anti-cancer drugs and inhibition of ferroptosis." (PMID 36874967, 2023). "Circ_0067934 reduced tumor cell ferroptosis via modulating miR-545-3p/SLC7A11 pathway and promoted tumor progression via miR-1301-3p/HMGB1 in thyroid cancer." (PMID 38152652, 2023).
tumor (continued). "Compared to that in peritumor tissues, the expression of ferroptosis-inducing genes, including PTGS2, ALOX12, TFR2, and HMOX1, was decreased in tumor tissues, whereas ferroptosis-suppressor genes, including SLC7A11 and GPX4, were increased." (PMID 37554285, 2023). "In contrast, the highly expressed lncRNA SLC16A1-AS1 in CCRCC inhibits ferroptosis by sponge-adsorbing the tumor suppressor gene miR-143-3P and upregulating the expression of the key protein of ferroptosis-SLC7A11." (PMID 36936418, 2023). "SLC7A11 overexpression promotes phospholipid peroxidation, which inhibits ferroptosis events in various tumor cells." (PMID 36846713, 2023). "Our data from animal studies suggested that the oxidizing environment in the blood should select against circulating tumor cells (CTCs) with high SLC7A11 expression." (PMID 37339981, 2023). "Recent studies revealed that SLC7A11 overexpression promotes tumor growth partly in suppressing ferroptosis." (PMID 36829917, 2023). "Up‐regulated KIAA1429 and SLC7A11 mRNAs were demonstrated in tumours in contrast to normal specimens across TCGA‐LIHC patients." (PMID 37830241, 2023). "To validate the biological function of SLC7A11 in ccRCC, we first confirmed high expression of SLC7A11 in tumor tissues using paired samples from the TCGA database." (PMID 37427103, 2023). "Results showed that the size and number of tumour spheroids were reduced after VD treatment, but overexpression of SLC7A11 alleviated this inhibition upon performing VD intervention and overexpression of SLC7A11 simultaneously." (PMID 36846715, 2023). "Deletion of Slc7a11 triggers tumor-selective ferroptosis and suppresses the growth of pancreatic ductal adenocarcinoma." (PMID 37061535, 2023). "In the first study, tamoxifen-induced whole-body Slc7a11 KO after tumor appearance led to increased survival." (PMID 37770957, 2023). "Of note the cg06690548 probeset methylation was negatively correlated (r ≤ −0.4; p ≤ 0.05) with SLC7A11 expression in 17 tumor types." (PMID 37397501, 2023). "By immunohistochemical staining of 32 pairs of tumor and para-cancer tissues from our hospital, we found that the expression levels of TFRC (P < 0.0001) and SLC7A11 (P < 0.0001) in tumor tissues were significantly higher than those in para-cancer tissues." (PMID 37940859, 2023). "Blocking SLC7A11-mediated cystine uptake in combination with immunotherapy synergistically enhances CD8+ T cell-mediated anti-tumor activity and promotes ferroptotic cell death." (PMID 38007476, 2023). "Ferroptosis plays a vital role in clinical tumour drug resistance, and its inhibitor solute carrier family 7 member 11 (SLC7A11) is a promising target to overcome resistance in conventional cancer therapy." (PMID 37344500, 2023). "We further performed a pancancer analysis of SLC7A11 and found higher expression of SLC7A11 in some urology-related tumours (ACC, KIRC, KICH, KIRP, PRAD, and TGCT) than in corresponding normal tissues." (PMID 37919768, 2023). "Glutamic acid produced by glutamine hydrolysis can be exported from tumor cells through transporters such as recombinant solute carrier family 7, member 11 (SLC7A11 or xCT)." (PMID 37164974, 2023). "Immunohistochemical analysis revealed that sulfasalazine markedly reduced the expression of the proliferative markers Ki-67 and SLC7A11 in the tumor tissues." (PMID 37460542, 2023). "Mechanistically, we found that METTL9 promoted tumor progression by upregulating the expression of SLC7A11, which subsequently decreases lipid oxidative damage and enhances antioxidant capacity, thereby inhibiting tumor-cell ferroptosis." (PMID 38017014, 2023). "Strikingly, although high overexpression of SLC7A11 promoted primary tumor growth, it significantly suppressed metastasis." (PMID 37339981, 2023). "We observed that in nearly all types of cancers, the expression level of SLC7A11 in tumor tissues is significantly higher than that in normal tissues." (PMID 38132439, 2023).
tumor (continued). "Mechanistically, the results of CUT&Tag and luciferase reporter assays showed that CEBPG inhibited ferroptosis of tumor cells by upregulating SLC7A11, a negative regulator of ferroptosis, thus accelerating the progression of OC." (PMID 37210575, 2023). "Consistent with this, our data showed that high overexpression of SLC7A11 promoted primary tumor growth." (PMID 37339981, 2023). "CD8+ T cells promote ferroptosis in tumor cells by releasing interferon-gamma (IFN-γ) and suppressing the expression of SLC3A2 and SLC7A11 in tumor cells." (PMID 37238692, 2023). "Erastin treatment led to increased ChaC glutathione specific gamma-glutamylcyclotransferase 1 (CHAC1) staining and decreased recombinant solute carrier family 7, member 11 (SLC7A11) staining in sham tumor tissue that were well responsive to erastin." (PMID 36967385, 2023). "Elevated expression levels of SLC7A11 in tumor cells contribute to tumor invasion and metastasis, which are also correlated with poor cancer prognosis." (PMID 37545500, 2023). "As a ferroptosis suppressor, SLC7A11 up‐regulation facilitates tumour growth partially via attenuating ferroptosis." (PMID 37830241, 2023). "Many ferroptosis‐related factors (e.g., NRF2, SLC7A11) are upregulated by tumor resistance mechanisms, among which EMT seems to play a prominent role." (PMID 36658724, 2023). "Meanwhile, western blot to detect ferroptosis‐associated markers of degrasyn‐treated HepG2 cells and xenograft tumor samples showed that key markers of ferroptosis, SLC7A11, and GPX4 decreased obviously." (PMID 37492786, 2023). "We further performed in vivo experiments, demonstrating that the weight and volume of tumours derived from CCSCs were decreased in the VD and sh-SLC7A11 groups." (PMID 36846715, 2023). "The result indicated that high SLC7A11 expression was statistically significant related to advanced tumor stage." (PMID 36874967, 2023). "We found that SLC7A11 is differentially expressed in most urinary system-related tumours and is often highly expressed in tumour tissues." (PMID 37919768, 2023). "Radiation therapy (RT) has been linked to inducing ferroptosis in tumours through diverse pathways, such as ROS production, GSH depletion, ACSL4 upregulation, and SLC7A11 inhibition." (PMID 38273826, 2023). "A study showed that the deletion of SLC7A11 can induced tumor-selective ferroptosis and inhibited PAAD progression." (PMID 37369808, 2023). "As an RNA-binding protein, PCBP2 is able to bind and stabilize the expression of SLC7A11 mRNA, inhibiting malignancy ferroptosis and promoting tumor progression." (PMID 37868994, 2023). "DNA damage-induced ataxia telangiectasia mutated (ATM) kinase activated by radiotherapy transcriptionally inhibits the expression of SLC7A11 to promote tumor ferroptosis." (PMID 37714846, 2023). "Online databases, including GSE14520, ICGC and TCGA‐LIHC, revealed that the expression of SLC7A11 in tumor tissues was significantly higher than that in normal tissues, and consistent results were obtained through IHC staining and western blotting." (PMID 36442849, 2023). "Inactivation of BAP1 in tumor cells results in increased expression of SLC7A11, leading to enhanced cystine uptake, GSH synthesis, and resistance to ferroptosis." (PMID 37552314, 2023). "Recent research has found that treatment techniques, which including immunotherapy and radiotherapy, trigger tumor cells ferroptosis to improve tumor suppression by altering SLC7A11 expression." (PMID 36903458, 2023). "Radiotherapy-activated ATM and IFNγ-induced STAT1 signalling jointly repress SLC7A11 to reduce cystine uptake and enhance tumor lipid peroxidation and ferroptosis." (PMID 37714846, 2023).